HLA-G (major histocompatibility complex, class I, G)
Diseases named in the same sentence as HLA-G in open-access papers (continued):
Sharing a sentence is not in itself a finding about the gene and the disease.
tumor (continued). "Increased numbers of HLA-G+ T cells and NK cells were detected in the peripheral blood of breast cancer patients, which are conducive to tumor development." (PMID 37627278, 2023). "Currently, HLA-G is considered as a novel immune checkpoint that is neo-expressed in tumor cells and promotes tumor immune escape." (PMID 37875821, 2023). "Abnormal expression of HLA-G by tumor cells can inhibit killing of tumor cells by T cells and antigen-presenting cells." (PMID 37138865, 2023). "Studies in animal models have shown that the use of anti-HLA-G blocking antibodies can effectively restore immunity against HLA-G-expressing tumor cells in vivo." (PMID 38162657, 2023). "High HLA-G tissue expression is often correlated with poorer disease status e.g. tumor size, nodal status, and stage as well as with inferior clinical outcome in terms of PFS and OS." (PMID 37283737, 2023). "HLA-G has been shown recently to play important roles in immune tolerance of organ transplants, immune escape of tumor cells and viruses, and fetus-maternal tolerance leading to protection of fetus from attack by the maternal immune system." (PMID 36911734, 2023). "A better insight into the relationship between checkpoint HLA-G and cytokines is to more effectively implement these tumour immunotherapy approaches, including anti-HLA-G neutralising antibodies and anti-HLA-G CAR-T cells." (PMID 36053326, 2023). "In terms of HLA expression, HLA-A, HLA-B, HLA-C, HLA-E, HLA-F, HLA-G, and HLA-J were significantly more highly expressed in C2 than in C1, indicating that tumour subtypes differ in the activation of immune cells." (PMID 37691922, 2023). "It is thought that tumor cells are protected from NK cells and cytotoxic T lymphocytes by expressing HLA-G, which is a tumor-induced immune escape mechanism." (PMID 37735675, 2023). "Particularly, immune cells infiltrating the tumor microenvironment can also exhibit HLA-G expression." (PMID 37627278, 2023). "This Nb‐CAR.BiTE‐γδT therapy can overcome HLA‐G and PD‐L1 dilemma and even kill tumor cells with inadequate antigen expression, resulting in potent anti‐tumor activity without apparent toxicity." (PMID 37078788, 2023). "In healthy tissues, HLA-G plays a protective immunosuppressive role, whereas, under neoplastic conditions, HLA-G allows tumor progression by being overexpressed in cancer cells." (PMID 38067396, 2023). "For further insights into the regulatory mechanisms of HLA-G in tumor immune evasion, please refer to the comprehensive review by Liu." (PMID 37627278, 2023). "Upon the formation of sHLA-G dimers, the activity of HLA-G molecules is increased, enhancing their binding affinity for ligand ILT-2/ILT-4, which is expressed by tumor-associated white blood cells." (PMID 37103820, 2023). "HLA-G is rarely expressed in normal cells and mainly found in tumor cells, as a ligand, it interacts with LIRB1 receptor with the highest affinity." (PMID 36882399, 2023). "In this study, we observed detectable sHLA-G levels in approximately half of the samples (47.1%), contrasting with the high HLA-G detection frequency (97.27%) in the tumor microenvironment." (PMID 37569841, 2023). "We identified HLA-G-specific regions and/or extended haplotypes associated with: (i) PTC histological and prognosis features, (ii) HLA-G expression in tumor specimens, and (iii) soluble plasma HLA-G detection before thyroidectomy." (PMID 37629044, 2023). "HLA-G gene plays an important role in immune tolerance, assisting immune escape of tumor cells, and decrease of transplant rejection." (PMID 36911734, 2023). "The generation of a transient hypoxic state is a normal phase of physiological placentation, and hypoxia has been shown to be a strong inducer of HLA-G expression in trophoblast and in tumor cells." (PMID 36768880, 2023). "In cancer, there is a correlation between HLA-G expression in both, tumor and tumor-infiltrating cells and unfavorable prognostic factors including higher tumor grade." (PMID 38162657, 2023).
tumor (continued). "These anti-HLA-G CAR-NK showed tumor cytotoxicity in orthotopic xenograft models of triple negative breast cancer and glioblastoma, developed in NSG mice." (PMID 37388731, 2023). "HLA‐G can inhibit the functions of NK and T cells, suppress the immune response, help tumour cells escape immune surveillance, and lead to poor prognosis of NSCLC patients." (PMID 36408734, 2023). "Major histocompatibility complex, class I, G (HLA-G) has also been detected in various types of PitNETs, primarily in lactotroph PitNETs suggesting tumour immuno-surveillance suggesting tumour immune-surveillance issue." (PMID 36774501, 2023). "The PTEN/PI3K pathways are responsible for HIF-1-mediated upregulation of CTLA-4, PD-L1, and HLA-G checkpoint molecules in several different mice and human tumor cell lines." (PMID 35158804, 2022). "In this scenario, HLA-G is usually up-regulated and produced by tumor cells and tumor-infiltrating leucocytes." (PMID 35328349, 2022). "In patients with CLL, blocking HLA-G on tumor cells is considered to be an effective means of sensitizing NK cell immunotherapy." (PMID 37078002, 2022). "Finally, HLA-G expression is down-regulated in different autoimmune and inflammatory diseases and induced or up-regulated in viral and microbial infections and in cancer, where it may be considered a tumor-associated antigen." (PMID 35328349, 2022). "The expression levels of HLA‐G and its isoforms profiles vary among tumor types, metastasis status, and disease outcome." (PMID 35759240, 2022). "Face-3 of HLA-G expression is restricted to the invasive extravillous trophoblasts of the decidua, and to tumor cells." (PMID 35214796, 2022). "This complex regulatory network for the control of the HLA-G expression can be altered to induce or enhance the immune evasion of tumor cells, but also of infectious pathogens, e.g. viruses, bacteria and parasites." (PMID 35237271, 2022). "Our group extensively studied HLA-G as a tumor escape mechanism in NB, which is the most common pediatric extra-cranial solid tumor in childhood." (PMID 35328349, 2022). "A previous study showed that the overexpression of HLA-G molecules on the surface of tumour cells affects tumour-specific T cell immunity, and upregulate the expression of ILT2 on tumour-infiltrating CD8+ T cells in the cancer microenvironment." (PMID 35924232, 2022). "Recent studies also showed that HLA-G regulates trophoblast invasion, a key parameter of placental development in normal and tumor conditions." (PMID 35203462, 2022). "The reason for this discrepancy lies mainly in two points: inter- and intra-tumor heterogeneity and the different methodological approaches used for detecting HLA-G." (PMID 35154112, 2022). "HLA-G expression can directly help tumor cells escape immune surveillance through receptor binding, impairment of chemotaxis, and a mechanism known as trogocytosis." (PMID 36311782, 2022). "We showed that some miRNA and target gene levels correlated with the HLA-G mRNA and protein levels in the tumor microenvironment." (PMID 35774498, 2022). "Our previous studies support that upregulation of HLA-G expression in the tumour microenvironment plays a key role in early cervical carcinogenesis." (PMID 35924232, 2022). "The presence of HLA-G in tumor tissue (25.5% of patients) was also reported, and the presence of HLA-G correlated with worse patient survival (p<0.0001)." (PMID 35154112, 2022). "The expression of HLA-G in liver tumors or the high-level expression of sHLA-G in HCC patients can free tumor cells from the immune response and inhibit the properties of immune cells such as T8 lymphocytes, NK cells, B cells, and dendritic cells." (PMID 36176778, 2022). "In contrast, a different RCC tumor lack HLA-G expression, but exhibit heterogeneous staining of ILT4." (PMID 35185904, 2022). "In cancer, increased HLA-G levels can alter the immunosurveillance mechanism, favoring tumor immune escape." (PMID 35774498, 2022).
tumor (continued). "Firstly, it suppresses the expression of activating ligands for NKG2D NK cell receptors, and secondly, it induces the expression of the human antigen-G (HLA-G) molecule on tumour cells." (PMID 35806034, 2022). "In cancer, HLA-G and PD-L1 expressed by tumor cells have been shown to inhibit different populations of T cells." (PMID 35222373, 2022). "HLA-G expression in tumor cells and virus-infected cells, as well as the release of soluble HLA-G leads to escape from host immune surveillance." (PMID 35237271, 2022). "In fact, some of these studies, clearly show a decrease in immunocompetent cells in an HLA-G rich tumor microenvironment, emphasizing the tolerogenic role of this molecule." (PMID 35154112, 2022). "It is noteworthy that the expression intensity of the HLA-G protein had an impact on clinical relevant parameters, such as tumor staging/grading, disease progression and patients’ survival." (PMID 35185904, 2022). "HLA-G with its immunosuppressive functions hampers the anti-tumor immunity and potentiates the cancer growth and its metastatic process." (PMID 35626255, 2022). "When expressed on tumor cells, HLA-G and HLA-E were shown to interact with inhibitory receptors expressed on T cells and NK cells, negatively affecting cytotoxic functions of both CD8+ T cells and NK cells." (PMID 36612267, 2022). "Accumulated evidence have showed that HLA-G is abnormally highly expressed in a variety of tumor cells and is involved in immune escape of tumors." (PMID 35185887, 2022). "A correlation of HLA-G expression with disease progression, tumor size and in some cases also with prognosis of RCC exists." (PMID 35185904, 2022). "Another study also showed intratumoral heterogeneity in ccRCC patients with very heterogeneous staining pattern for HLA-G ranging between 37 – 70% of HLA-G throughout one tumor using IHC as well as for ILT4, which preferentially binds HLA-G." (PMID 35185904, 2022). "Similar results were found for the +3187G/G genotype, which increases the HLA-G mRNA stability and, therefore, HLA-G molecule expression, thus favoring tumor progression, as expected." (PMID 35154112, 2022). "As a consequence, the hypoxic-dependent overexpression of HLA-G also contributes to tumor escape from immune surveillance." (PMID 35910347, 2022). "Conversely, MAP4K4 depletion decreased PM association of proteins involved in tumor immune evasion (CD155, CD276, and HLA-G), in solute influx regulation (CLIC1, SLCs, and ABCCs) and cell migration (CD155 and CD276)." (PMID 35296518, 2022). "Tregs, DCs and tumor cells can produce and release the anti-inflammatory cytokine interleukin 10 (IL-10), which can promote the expression of HLA-G." (PMID 35185904, 2022). "Next to membranous HLA-G expression, sHLA-G isoforms were often elevated in plasma or serum samples of tumor patients." (PMID 35185904, 2022). "We had a lower occurrence of HLA-G-positive tumours than the published studies with a > 0% cut-off with 9.0% in our cohort compared with 70.6 and 65% in two Chinese populations and 20.3% in a Dutch population, thereby in more accordance with our study." (PMID 35027037, 2022). "Analysis of mRNA and protein levels revealed a discordant HLA-G mRNA and protein expression pattern frequently occurred suggesting a post-transcriptional regulation of HLA-G in this tumor entity." (PMID 35185904, 2022). "Tumor cells express HLA-G de novo to evade immune surveillance, similar to the immunosuppressive function seen in the placenta." (PMID 35865547, 2022). "Ectopic expression of HLA-G molecule in cervical lesions helps tumour cells escape immunosurveillance by generating inhibitory signals." (PMID 35924232, 2022). "Beside HLA-G localization on tumor cells, it can also occur in EVs, e.g. in exudates or serum/plasma from cancer patients." (PMID 35185904, 2022). "In multiple tumor entities, the expression of HLA-G-regulating miRNAs has been shown to be inversely correlated with HLA-G." (PMID 36334153, 2022).
tumor (continued). "Recent medical investigations suggest that HLA-G can be used as a biomarker in the diagnosis, treatment, and prognosis of different neoplasms." (PMID 35626255, 2022). "Expression of ILT2, which binds to human leukocyte antigen (HLA)-G, on NK cells and invariant NK T cells contributes to tumor tolerance by reducing the proliferative and cytotoxic activities of these cells." (PMID 36097216, 2022). "For example, HLA-G molecules exist at high levels in the tumor environment and have excellent potential to become immune checkpoint therapy; the silent mutation or deletion of HLA molecules has proved to be a relatively common phenomenon in cancer." (PMID 35754800, 2022). "In detail, the blocking of PD-1/PD-L1 interaction, in association with that of HLA-G/ILT2, is able to rescue anti-tumor CTL functions." (PMID 35328349, 2022). "In malignancies, HLA-G expression can directly help tumor cells escape immune surveillance through receptor binding, impairment of chemotaxis, and a mechanism known as trogocytosis." (PMID 36311782, 2022). "The GEIA study aims to investigate the impact of HLA-G tumor expression on the efficacy of cancer immunotherapy in patients with solid cancers to evaluate the presence of resistance to the current immunocheckpoint inhibitor strategy (NCT04300088)." (PMID 36559230, 2022). "The same happens when contact occurs between a tumor cell expressing HLA-G on its membrane and a NK cell." (PMID 35154112, 2022). "HLA-G expression was strongly associated with disease progression, whereas IDO expression correlated only with the extranodal spread of tumor." (PMID 35328349, 2022). "While LILRB1 and LILRB2 recognize the conserved α3 and B2M domains in most HLA haplotypes, HLA-G has emerged as an interesting binding partner due to its more restricted expression on tumor cells." (PMID 35865547, 2022). "Immunohistochemistry revealed 100% tumor PD-L1 expression and HLA-G positivity, but tumor cells were HLA-A-negative." (PMID 35681761, 2022). "It is common that up-regulation of inhibitory NK receptor ligands such as KIR2DL4, immunoglobulin-like transcript 2(ILT2) and ILT4 human leukocyte antigen g(HLA-G) in tumor cells is more common in immune stress, whereby cancer cells escape NK cell killing." (PMID 37078002, 2022). "HLA-G has been proposed as an immune checkpoint (IC) molecule due to its crucial role in tumor progression, immune escape, and metastatic spread." (PMID 35328349, 2022). "HLA-G, a member of the HLA- Class IB family, has a membrane-bound and soluble (sHLA-G) form, an immunomodulatory molecule that participates in tumor escape by promoting the Th2 cytokine environment and inhibiting immune effector cells." (PMID 36176778, 2022). "Escape: In this phase, high increase of HLA-G expression, together with other mechanisms takes place; this allows complete evasion of the immune system by the tumor." (PMID 35154112, 2022). "Aberrant induction of HLA-G expression in malignant cells represents one of the key factors that contribute to tumor immune escape and progression." (PMID 35626255, 2022). "For instance, several studies demonstrated that the combination of HLA-class I downregulation and HLA-G expression in tumours was correlated with poor clinical patient outcome in multiple carcinoma types." (PMID 34361031, 2021). "HLA-G is a tolerogenic HLA-class Ib molecule enabling the escape of tumor cells from immune surveillance." (PMID 34069335, 2021). "Given the fact that HLA-G/ILTs interaction is conformation dependent, tumor cell surface native or conformational HLA-G expression be evaluated with assays such as flow cytometry is necessary." (PMID 34276691, 2021). "The abnormal tumor cell expression of HLA-G molecules is part of the strategy for evading host immune surveillance." (PMID 33767709, 2021). "The disparities between the reported percentages of HLA-G-positive tumour samples cannot be attributed to significant differences in HLA-G quantification methods." (PMID 34361031, 2021).
tumor (continued). "Tumour-infiltrating NK and CD8+ T cells were negatively associated with HLA-G expression, whereas infiltrating Tregs were positively correlated with HLA-G expression." (PMID 34361031, 2021). "Here, two separate cut-off values were chosen at which IHC tumour samples were deemed HLA-G positive." (PMID 34361031, 2021). "The percentage of HLA-G-positive tumour samples differed considerably between the included studies, ranging from 20 to 82%." (PMID 34361031, 2021). "Again, tumor cells in the JEG3-Sh-NLRP7 condition expressed less HLA-G and PD-L1, and mouse macrophages appeared to slightly infiltrate the JEG3-Sh-NLRP7 tumors but not the JEG3-Sh-CTL tumors." (PMID 34203890, 2021). "For example, human leukocyte antigen G (HLA-G) which provides immunity to foetuses in pregnant women but has been reported to be overexpressed in many tumor types." (PMID 34688033, 2021). "This upregulation of tumor HLA-G involves inhibition of DNMT1 and demethylation of transporter associated with antigen processing 1 promoter." (PMID 34663641, 2021). "To evaluate the role of HLA-G in tumor progression, we assessed the correlation between HLA-G expression and pathological stage in different tumor patients using the GEPIA database." (PMID 34276642, 2021). "We will discuss in detail on the role of HLA-G and the oncologic trogocytosis among tumor cells, immune-related cells, and mesenchymal stroma/stem cells in the immune evasion in the following subsections." (PMID 33668117, 2021). "The lower threshold value assumed that IHC tumour samples were HLA-G positive when ≥5% of the tumour cells stained for HLA-G expression." (PMID 34361031, 2021). "Here, we not only used databases and tissue arrays to confirm expression of HLA-G by tumor and normal cells, but we also used in vitro models to confirm the absence of toxicity induced by HLA-G CAR-NK cells." (PMID 34663641, 2021). "Based on different databases, the bioinformatics analysis showed that HLA-G was upregulated in most types of human tumor tissues or tumor cell lines." (PMID 34276642, 2021). "Studies have shown that most tumor cell lines, especially malignant melanomas, are positive for HLA-G mRNA, but some reports disagree." (PMID 33767709, 2021). "It is now widely accepted that HLA-G is a key molecule in the process of immune escape of cancer cells, which is ubiquitously expressed in the tumor environment." (PMID 34868081, 2021). "Although the effects of tumour HLA-G expression on clinical patient outcome remains enigmatic, overall it seems obvious that HLA-G can be expressed by tumour cells, albeit heterogenic within and between tumours." (PMID 34361031, 2021). "Previous studies in mice showed protective effects of HLA-G on transplant rejection and collagen-induced arthritis; furthermore, sHLA-G was shown to allow tumor evasion from immunosurveillance, with some of these effects being mediated by an expansion of MDSC." (PMID 35111157, 2021). "HLA-G test results vary greatly in different locations of HLA-G acquisition, between different tumors, or the same tumor in different laboratory test results." (PMID 34868081, 2021). "HLA-G is present in tumor tissues and/or infiltrating cells (including predominantly monocytes, macrophages and lymphocytes) but not in normal tissues." (PMID 33767709, 2021). "As a result, overestimation of HLA-G expression in tumour lesions is a realistic possibility, which in turn influences the HLA-G-related clinical outcome analyses in carcinoma patients." (PMID 34361031, 2021). "So, in order for HLA-G to exert a functional role in tumour progression, it will be in interaction with immune cells." (PMID 34361031, 2021). "We first identified that the mRNA expression levels of HLA-G were significantly upregulated in both most tumor tissues and tumor cell lines on the basis of in-depth analysis of RNAseq data." (PMID 34276642, 2021).